IDO1 (indoleamine 2,3-dioxygenase 1)
Diseases named in the same sentence as IDO1 in open-access papers (continued):
Sharing a sentence is not in itself a finding about the gene and the disease.
Obesity (continued). "Nevertheless, administration of exogenous Kyn significantly exacerbated HFD-induced obesity and insulin resistance, and whole-body knockout of Ido1 restored circulating Kyn levels and protected mice from obesity, which were opposite to the assumption." (PMID 35715443, 2022). "Collectively, our data support that obesity is coupled with IDO1 overexpression in mature adipocytes, thereby leading to the excessive production of Kyn." (PMID 35715443, 2022). "Herein, we demonstrated that mature adipocytes from subjects with obesity are featured by the overexpression of IDO1, thereby mediating tryptophan catabolism to produce excessive Kyn, which in turn exacerbates obesity and insulin resistance." (PMID 35715443, 2022). "Ido1 deficiency in adipocytes attenuated the increase of Kyn following high-fat-diet (HFD) challenge, thereby protecting the mice from obesity." (PMID 35715443, 2022). "Collectively these results suggest that GaELNs inhibit induction of brain inflammatory cytokines and reverses the high-fat diet induced obesity through regulating the IDO1-AHR axis signaling pathway." (PMID 35154484, 2022). "Because remarkable similarities between adipose expansion and growth of solid tumors have been observed, we evaluated the in vivo IL-6 dependency of IDO1 expression and activity in obesity." (PMID 34394118, 2021). "To investigate the role of IDO1 and its possible relationship with IL-6 in obesity, we induced the disease by feeding mice with a high fat diet (HFD)." (PMID 34394118, 2021). "Further mechanistic insights of the IL-22 signaling were given in a recent studies, where indoleamine 2,3-dioxygenase 1 (IDO), an enzyme that is present in many immune cells and activated during inflammation, was linked to the gut microbiota and obesity." (PMID 33178196, 2020). "It is noteworthy that TIGIT and IDO1 showed stronger co-expression with other immune checkpoints in normal group compared with obesity group." (PMID 33197880, 2020). "We hypothesized that SIRT1 might influence the phenotype and functions of DCs through the Ido1 pathway, ultimately leading to the polarization towards pro-inflammatory T cells in obesity." (PMID 39424786, 2024). "Mice deficient in IDO1, an enzyme that metabolizes TRP, were resistant to obesity." (PMID 36839388, 2023). "Depletion of Ido1 in adipocytes abrogates Kyn accumulation, protecting mice against obesity." (PMID 35715443, 2022). "Therefore, specific depletion of Ido1 in adipocytes protected mice from HFD-induced obesity by limiting Kyn production." (PMID 35715443, 2022). "Similar as above, IDO1 was markedly upregulated in the WATs originated from subjects with obesity." (PMID 35715443, 2022). "Therefore, our data indicated the existence of an aberrant interplay between IL-6 and IDO1 in obesity and the possibility to use IL-6R blockers for therapeutic purposes in obese patients." (PMID 34394118, 2021). "In the present study, we investigated the possible relationship between IL-6 and IDO1 in obesity." (PMID 34394118, 2021). "Because IL-6 is a cytokine widely recognized to play a major role in obesity and is also known to exert dichotomic effects on IDO1 expression, we investigated the possible effect of the cytokine on IDO1 expression and activity in the WAT of diet-induced obese mice." (PMID 34394118, 2021). "We next compared the obesity parameters in wild-type (WT) and Ido1−/− mice, both fed with HFD." (PMID 34394118, 2021). "Additionally, we sought to understand whether obesity or RES treatment could impact IDO1 expression in humans." (PMID 39424786, 2024). "Since the Ido1-aKO mice exhibited a dramatically increased lipolysis and decreased lipogenesis coupled with relieved adipocyte hypertrophy in the WAT, we assume that Kyn impairs lipid metabolism in adipocytes predisposing to the development of obesity upon sustained HFD challenge." (PMID 35715443, 2022).
Obesity (continued). "Therefore, targeting IDO1 for reducing Kyn production combined with Vit-B6 supplementation for promoting Kyn catabolism could be a viable strategy against obesity and insulin resistance in clinical settings." (PMID 35715443, 2022). "In addition to provide the evidence for the existence of a pathogenetic IL-6/IDO1 axis in obesity, our data suggested that IL-6 blockade by TCZ may represent a promising therapeutic option for obese patients." (PMID 34394118, 2021). "Given that IDO1 was one of the most highly upregulated genes in our profiling of ccRCC tumors from, subjects with obesity, we also evaluated the enzymatic activity of plasma IDO to determine if IDO changes were specific to the tumor microenvironment or if these could be detected peripherally." (PMID 32469992, 2020). "IDO-1 down-regulation by microbiota-derived butyrate in IECs, as demonstrated here, could be crucial for the fine-tuning of IDO-1 expression in healthy conditions and for the initiation of appropriate immune responses depending on the context: chronic inflammation, cancer, obesity or infections." (PMID 30619249, 2018). "We hypothesized that in patients with obesity, K/T ratio is mainly driven by IDO1 activity." (PMID 27327770, 2016). "In summary, these data shows that the effects of SIRT1 levels on BMDC phenotype correlated with IDO1 and an active KYN pathway, which are both affected in obesity." (PMID 39424786, 2024). "In consistent with the attenuated obesity phenotype, the HFD challenged Ido1-aKO mice exhibited significantly improved glucose tolerance and insulin sensitivity." (PMID 35715443, 2022). "The individual pathophysiological role c-Myc, cGAS/STING, IDO1, and AHR plays in inflammatory responses has been demonstrated in obesity and type 2 diabetes 69-71." (PMID 35154484, 2022). "IFN-γ induces the expression of IDO1, which in turn the metabolites generated as IDO1 dependent manner activate the AHR pathway that contributes to developing obesity." (PMID 35154484, 2022). "Although IDO1 overexpression has been noted in the WAT, small intestine and colon from subjects with obesity, less effort has been devoted to explore the exact cell type contributing to the superfluous Kyn production." (PMID 35715443, 2022). "In this case, altered IDO1 expression leads to Kyn accumulation, which enhances AhR/STAT3/IL-6 signaling in adipocytes to mediate obesity and insulin resistance." (PMID 35715443, 2022). "Thus our data indicated that the IL-6/IDO1 axis may play a pathogenetic role in a chronic, low-grade inflammation condition, and, perhaps most importantly, IL-6R blockade may be considered a valid option for obesity treatment." (PMID 34394118, 2021). "Kynurenine is increased in the serum of obese subjects, and IDO1 is upregulated in the liver and WAT in obesity." (PMID 31921154, 2019). "Due to the low-grade chronic inflammatory state occurring in obesity, it is not surprising that IDO1 gene expression is increased in the adipose tissue derived from subjects with obesity." (PMID 36771236, 2023). "Moreover, the expression of IDO1, kynureninase, KMO and KAT III [CCBL2] was increased in the omental adipose tissue of women with obesity compared to lean individuals, and their expression was induced by pro-inflammatory cytokines in human primary adipocytes." (PMID 36766803, 2023). "In contrast to the Ido1-lKO mice, the Ido1-aKO mice were resistant to HFD-induced obesity." (PMID 35715443, 2022). "Since IDO1 can be induced by proinflammatory factors, such as IFN-γ and TNF-α41, it is reasonable to assume that Kyn and IDO1 are upregulated by the obesity-induced low-grade chronic inflammation in a compensated manner." (PMID 35715443, 2022). "Plasma IDO activity was not altered (P = 0.9324) in a subset of ccRCC subjects (n = 37) by obesity status, suggesting that the IDO1 alteration is specific to the tumor microenvironment." (PMID 32469992, 2020).
Obesity (continued). "Thus, our nanoString screen suggests that in renal tumors from subjects with obesity, increases in CD36 and IDO1, with concomitant decreases in T cell-related CD7 and CCL21, are consistent with a host environment that favors tumor progression." (PMID 32469992, 2020). "Leptin is involved in neuroimmune interactions that link obesity, inflammation, and mood disorders, as it stimulates the release of proinflammatory cytokines such as IL-6, TNF-α, and IFN-γ, which are well-established activators of IDO1, thereby increasing the degradation of Trp through the KP." (PMID 41516008, 2025). "Lack of IDO1 expression ameliorated the disease in terms of weight gain and glucose tolerance but not of adipocyte hypertrophy, suggesting that Trp metabolism exerts pathogenetic rather than protective effects in obesity." (PMID 34394118, 2021). "Interestingly, mice lacking IDO1 expression in macrophages and neutrophils exhibited normal weight gain and insulin sensitivity in obesity." (PMID 31921154, 2019). "Of those changes identified in the tumor microenvironments of ccRCC subjects with obesity versus non-obese counterparts, those with the largest fold changes were CD36 (+2.514, P = 0.045), IDO1 (+2.46, P = 0.012), CFB (+2.0, P = 0.041), CD7 (-4.66, P = 0.046), and CCL21 (-5.28, P = 0.0097)." (PMID 32469992, 2020). "Unlike the conventional Ido−/− mice, the Ido1-lKO mice following a 12-week of HFD induction exhibited comparative bodyweight change and insulin sensitivity as their littermates, confirming that macrophages are not the critical target for IDO1 modulation of the development of obesity." (PMID 35715443, 2022).
COVID-19 (39 papers, 2020 to 2025). A disease caused by infection with severe acute respiratory syndrome coronavirus 2. "The pathogenic role of IDO1/IDO2 imbalance in COVID-19 and PACS should of course be considered within a wider and more complex scenario where different mechanisms occur, including other metabolic abnormalities involved in immune regulation." (PMID 35740354, 2022). "We hypothesize that IDO1 is necessary for a correct control of the vascular tone of pulmonary vessels, and its deficiency in COVID-19 might be related to the syndrome’s evolution toward vascular dysfunction." (PMID 35740354, 2022). "Furthermore, a diffuse enlargement of interstitial vessels was noted, suggesting a pathogenic role of IDO1 in inducing COVID-19 V/Q mismatch and silent/happy-hypoxia." (PMID 35740354, 2022). "In COVID-19-associated CRS, the immunoregulatory Trp-derived metabolites generated by IDO1 could be deficient and their absence could worsen the inflammatory events in COVID-19." (PMID 32636755, 2020). "Although these findings highlight mechanistic rationale for IDO1 inhibition in SARS-CoV-2 infection, clinical studies directly assessing IDO1-specific inhibitors in COVID-19 populations remain limited." (PMID 40949107, 2025). "While IDO1 inhibitors are well-characterized in oncology and infectious diseases, their application in COVID-19 is still emerging." (PMID 40949107, 2025). "The immunomodulatory function of the IDO1-KYN-AHR axis in COVID-19 has prompted interest in IDO1 inhibition as a potential therapeutic strategy." (PMID 40949107, 2025). "Four of these genes (ACE, KLF5, IDO1, and CDC25A) have been reported to be associated with the pathological mechanisms of COVID-19 and sarcopenia." (PMID 38978778, 2024). "Increased Trp metabolism and induction of IDO-1 in acute COVID-19 cases have been reported in several studies." (PMID 38802702, 2024). "In severe COVID-19 patients, the activation of AhR by IDO1-derived tryptophan metabolites acts as a biological defense mechanism." (PMID 39408347, 2024). "Several TCDD-inducible or MARylating (transferring only one moiety of ADP-ribose) PARP and also IDO1 genes are indeed up-regulated in COVID-19." (PMID 37486805, 2023). "Patients with mild/moderate illness showed significantly higher expression levels of IL-6, IL-1β, IL-10, CRP and IDO1 than COVID-19-free subjects." (PMID 37715121, 2023). "As Trp degradation in COVID-19 involves IDO1/TDO induction, the rise in salivary [Trp] can only reflect increased availability of the amino acid, arising most likely from a potential free plasma Trp elevation." (PMID 37486805, 2023). "In the case of COVID-19, the shift in the Trp/Kyn ratio must also be considered, which in inflammation and cancer has been mainly ascribed to the upregulation of IDO-1." (PMID 35203299, 2022). "Impairment of vascular-tone regulation and bioavailability of vasodilators (including IDO1 metabolites and NO) is considered central in the development of endothelial dysfunction and diffuse alveolar damage in different conditions, such as COVID-19." (PMID 35740354, 2022). "In the case of COVID-19, the data from Grunewald and Turski can lead us to consider some inflammatory mediators as potential intracellular inductors of IDO-1, the activation of which is the logical explanation for Kyn overproduction." (PMID 35203299, 2022). "A significantly different IDO1 expression pattern is observed in COVID-19 early/mild pneumonia and PACS patients, where most parenchymal blood vessels, both capillaries and venules, consistently show endothelial immunostaining." (PMID 35740354, 2022). "Autoimmune complications are common in COVID-19, and the possible role of IDO1/IDO2 imbalance in their development warrants further investigation." (PMID 35740354, 2022). "The CXCL10+ CCL2+ inflammatory macrophages displayed significantly higher expression of CXCL10, CXCL11, CCL2, CCL3, GBP1, and IDO1 in severe COVID-19, inflamed RA, and CD compared to the FCN1+ macrophages." (PMID 33879239, 2021).
COVID-19 (continued). "Among the Age-Up genes that were upregulated in severe COVID-19 patients, IDO1 was the most significant." (PMID 33397975, 2021). "The comparison between COVID-19 patients showed that those with severe symptoms had borderline or significantly (for IDO1) lower values vs. those with mild symptoms." (PMID 34299101, 2021). "A possible aberrant activation of AhR and IDO1 has been put forward to explain the symptomatology of COVID-19 patients, and a recent study identified AhR signaling as a common host response to infection by coronaviruses responsible for lung pathogenesis." (PMID 33322584, 2020). "As the diagram suggests, IDO1 and hence KP activity are likely to feature prominently in COVID-19 pathophysiology." (PMID 33063092, 2020). "Furthermore, dexamethasone, a clinical agent used in COVID-19 treatment, exerts partial inhibitory effects on IDO1 and AHR through glucocorticoid receptor-mediated pathways, contributing to reduced cytokine storm severity and enhanced viral clearance." (PMID 40949107, 2025). "Additionally, predominant IDO1 expression can be observed in lung ECs of COVID-19 patients, in whom elevated serum KYN and QUNA concentrations have been reported." (PMID 38221627, 2024). "Recent histologic studies have shown that indoleamine 2,3-dioxygenase (IDO) is differentially expressed in the pulmonary vasculature in patients with COVID-19, and that IDO1 is predominantly present in lung tissues of patients with early/mild pneumonitis and those suffering from prolonged pneumonia." (PMID 38978778, 2024). "Severe COVID-19 patients present a concomitant significant increase in 1) IDO-1 activity, 2) increased production of KP metabolites, and 3) high levels of proinflammatory mediators including TNF-α and macrophage inflammatory protein-1 α (MIP-1α) both part of the cytokine storm." (PMID 38802702, 2024). "COVID-19 could increase the presence of other pathogens and comorbidities that activate AhR via IDO-1-dependent mechanisms." (PMID 38802702, 2024). "They demonstrated that IFN-γ and its specific ISGs (chemokine C-X-C motif ligand 10 —CXCL10— and Indoleamine 2,3-Dioxygenase 1 —IDO1—) are more expressed in patients with mild COVID-19 presentation, but they tend to decrease in children with severe clinical manifestations, particularly in MIS-C." (PMID 37240926, 2023). "Therefore, AhR activation by IDO1-derived tryptophan metabolites in patients with severe COVID-19 can be regarded as a biological defense mechanism against severe infection." (PMID 35463998, 2022). "This confirms the critical role of the IDO1 gene network in COVID-19-exaggerated cytokine release." (PMID 36589459, 2022). "This suggests that, in parallel with the increase in cytokines-mediated inflammation, which in symptomatic COVID-19, drives the so-called “cytokine storm”, there is a concomitant increment of an IDO-1-mediated transformation of the essential amino acid Trp in Kyn and derived metabolites." (PMID 35203299, 2022). "Another study also reported similar findings showing elevated levels of IDO-1 in COVID-19 patients." (PMID 34621138, 2021). "The immune modulating effects of IDO1 may also be of importance in infectious diseases like COVID-19." (PMID 34943063, 2021). "Moreover, the total percentages of ILT3+, PD-L1+ and IDO-1+ Mo-MDSC were increased in severe COVID-19 patients compared to both mild patients and healthy donors." (PMID 33692788, 2021). "The potential role of the IDO1 pathway in COVID-19 has been recently described." (PMID 33322584, 2020). "The IDO1 inhibitors have therapeutic utility in various diseases and, in the near future, may be of use in the treatment of peripheral neuropathy observed in patients with leprosy, COVID-19, or both." (PMID 35281455, 2022).
COVID-19 (continued). "It is not possible to draw a conclusion from these data on whether KYN is more of an indicator of a protective mechanism at the starting point of pulmonic disease, or a pathfinder to a severe course of COVID-19 referring to immunosuppressive action and oxidative stress perturbation effects of IDO1." (PMID 34943063, 2021). "Nevertheless, the immunosuppressive effects of IDO1 may outperform all positive effects, by exponentiation of an insufficient type I interferon production by the innate immune system in the early phase of severe COVID-19." (PMID 34943063, 2021). "COVID-19–induced inflammation elevates key cytokines such as IFN-γ, IL-1β, and IL-6, which potently induce IDO1 expression in immune cells including macrophages, fibroblasts, and dendritic cells." (PMID 40949107, 2025). "In this context, our results show a statistically significant increase in the expression levels of IL-6, CRP, IDO1 and ACE2 in patients with severe disease compared to patients with mild and moderate COVID-19." (PMID 37715121, 2023). "Transcripts of genes encoding 6 biomarkers, IL-1β, IL-6, IL-10, C-reactive protein, IDO1 and ACE2, were measured by RT‒qPCR in saliva samples of patients and COVID-19-free individuals." (PMID 37715121, 2023). "MDSC display abundant immune suppressive mechanisms including IL-10, TGF-β, Arg-1, IDO-1, ILT3, COX-2, PD1L, and others, all of which were clearly increased in COVID-19 patients in this study." (PMID 33692788, 2021). "The observed imbalance of IDO1 and IDO2 expression in COVID-19 may be ascribed to different mechanisms." (PMID 35740354, 2022). "Intriguingly, PD-L1-, ILT-3-, and IDO-1-expressing monocytic MDSC were the dominant producers of IL-6 and IL-10, which correlated with the increased inflammation and accumulation of regulatory B and T cell subsets in severe COVID-19 patients." (PMID 33692788, 2021). "A range of selective and potent TDO, IDO1, and IDO2 inhibitors are currently under investigation in cancer research and information from this field may be translationally utilized for new personalized therapies for patients suffering from COVID-19 and PACS." (PMID 35740354, 2022). "Interestingly, IDO1 inhibitors suppress the COVID-19-induced pro-inflammatory cytokine release, including TNF-α, IL-6, IL-1α and IL-1β in isolated PBMCs derived from COVID-19-infected rhesus macaques and lower mortality among critically ill patients with COVID-19." (PMID 36589459, 2022).